RNU6-61P (RNA, U6 small nuclear 61, pseudogene)
Synonyms: RNU6-61
Gene: Small nuclear RNA gene on chromosome 13 (80,369,426 to 80,369,534, reverse strand). Ensembl gene ENSG00000202398.
Homologues: Orthologues: chimpanzee U6 (97% identical), rat U6 (92% identical), macaque U6 (88% identical), guinea pig U6 (87% identical), dog U6 (86% identical), rabbit U6 (84% identical). Paralogues in human: RNU6-7 (93% identical), RNU6-8 (93% identical), RNU6-1 (92% identical), RNU6-15P (92% identical), RNU6-2 (92% identical), RNU6-21P (92% identical), RNU6-3P (92% identical), RNU6-4P (92% identical), RNU6-5P (92% identical), RNU6-6P (92% identical), RNU6-9 (92% identical), RNU6-11P (91% identical), and 1286 more.